IL1B (interleukin 1 beta)
Diseases named in the same sentence as IL1B in open-access papers (continued):
Sharing a sentence is not in itself a finding about the gene and the disease.
epilepsy (continued). "In this study the IL-1β monoclonal antibody that was chelated to magnetic nanoparticles was beneficial for targeted epilepsy treatment." (PMID 30514296, 2018). "The level of IL-1β in the brain tissue of patients was positively correlated with the severity of preoperative epilepsy, and a clinical study revealed the expression of IL-1β/IL-1R1 in the glial cells and neurons of drug-refractory epilepsy patients." (PMID 30514296, 2018). "An E/I imbalance has also been demonstrated in other neurological diseases characterized by excessive IL-1β levels, such as multiple sclerosis and epilepsy." (PMID 29674955, 2018). "Twenty years of research have indeed indicated that IL-1β is involved in several brain diseases, including multiple sclerosis, Alzheimer disease, epilepsy, stroke, and even neurodevelopmental disorders such as schizophrenia and autism." (PMID 29674955, 2018). "Free fatty acids used in epilepsy treatment can reduce IL-1β levels, possibly through activation of PPARα, and the ketogenic diet metabolite βHB reduces inflammation." (PMID 30424795, 2018). "Activated microglia is a prominent source of proinflammatory factors such as TNF-α, IL-1β, both of which are neurotoxic and proved to promote hyperexcitability in epilepsy." (PMID 29312110, 2017). "α-Asarone decreased TNF-α, IL-1β in the rat epilepsy model as well as in activated primary cultured microglia." (PMID 29312110, 2017). "IL1β & IL6 are found to have pro-epileptogenic properties in animal models for epilepsy, particularly, IL1β, which affects neuronal Ca2+ influx through NMDA dependent signalling." (PMID 29162878, 2017). "In this study, we focused on IL-1β, a pro-inflammatory cytokine, strongly deregulated in TSC human brain and known to play a key pathogenic role in human epilepsy." (PMID 27122151, 2016). "In particular, activation of the pro-inflammatory axis formed by interleukin-1ß (IL-1β) and its cognate receptor IL-1R type 1 has been described in patients with epilepsy as well as in experimental models of epilepsy." (PMID 27281030, 2016). "On the other hand, IL-1β levels showed both graded brain region-specific differences and epilepsy-related effects." (PMID 27737716, 2016). "We have shown for the first time that transcriptional levels of two important inflammatory biomarkers related to epilepsy, il1b and cox2, are upregulated in the brain of zebrafish after PTZ-induced seizures." (PMID 26961169, 2016). "Despite inflammatory processes, IL-1β was involved in the entire process of epilepsy; however, the postictal suppression (PS) phase, a common and important period following SE, is an important period of IL-1β action." (PMID 26925269, 2016). "IL-1β exerts a pro-convulsive effect with worsened and prolonged seizure activity in rodent epilepsy models." (PMID 25078263, 2015). "Inhibition of leukocyte infiltration of the blood−brain barrier prevented experimental epilepsy, and IL-1β antagonists reduced induced seizures." (PMID 26464976, 2015). "For epilepsy and bipolar disorder, overlapping results regarding the cytokine system have been reported, namely, alterations of IL-1β, IL-2, IL-4, IL-6, and TNF-α." (PMID 24757498, 2014). "In bipolar disorders as well as in epilepsy and febrile seizures, IL-1β levels have been reported to be increased." (PMID 24757498, 2014). "We found a significantly lower Kir4.1 expression in tumor tissue of patients with epilepsy, which paralleled the increased expression of IL-1β." (PMID 23270518, 2012). "The higher plasma levels observed in this study of IL-6, IL-1β, IL-2, and IL-8, also support the concept that innate immunity is chronically activated in epilepsy." (PMID 23293627, 2012). "In epilepsy patient plasmas, we found that concentrations of anti-inflammatory sICAM5 are reduced (p = 0.002) and pro-inflammatory IL-1β, IL-2, and IL-8 are elevated." (PMID 23293627, 2012).
epilepsy (continued). "An increase in inflammatory cytokines, IL-1β in particular, has been reported in the CNS and plasma in experimental models of seizures and in clinical cases of epilepsy." (PMID 21087489, 2010). "In epilepsy, on the one hand, pyroptosis can promote the occurrence of ferroptosis; IL-1β produced following neuronal pyroptosis may exacerbate ferroptosis by influencing the expression of genes related to iron metabolism." (PMID 41513612, 2026). "However, a study of the role of intraventricular injection of IL-1β in epilepsy found that IL-1β had protective and antiepileptic effects." (PMID 39858450, 2025). "Conversely, inhibiting IL-1β signaling pathways can lessen both the intensity and frequency of seizures, indicating that IL-1β may directly contribute to the development of epilepsy and the initiation of seizures." (PMID 41328216, 2025). "In any case, as an inflammatory factor that is important for both epilepsy and schizophrenia, although its role in epilepsy is controversial, we still believe that it is of great value to further investigate the role of IL-1β in the neuroimmune mechanism of POE." (PMID 39858450, 2025). "A growing number of studies have revealed altered levels of IL-1β in seizures and epilepsy." (PMID 41155637, 2025). "Additionally, it has been shown that lesion-associated epilepsy causes further activation of inflammasomes through the HMGB1/TLR4 and IL-1β/IL-1R1 signaling pathways." (PMID 40217546, 2025). "Clinical studies have reported that IL-1β is expressed in lesions of cortical dysplasia in patients with epilepsy and that the number of IL-1β-positive cells correlates with seizure frequency, thus the expression of IL-1β is an important factor in epileptogenesis." (PMID 38914629, 2024). "For example, elevated levels of IL-6 and IL-1β have been found in epilepsy patients." (PMID 39091611, 2024). "However, this increased il1β expression was probably too weak to be detected by qRT-PCR analysis of brain RNAs, showing again the differences between genetic and pharmacological epilepsy models." (PMID 38667299, 2024). "Notably IL-1β, shown to be deeply involved in the pathogenesis of epilepsy, alters pericyte morphology and facilitates the formation of pericyte–microglia aggregates in ex vivo hippocampal slices." (PMID 38338969, 2024). "A significant increase in proinflammatory cytokines, including IFN-γ, IL-1β, IL-6, IL-10, IL-12, and TNFα, was observed after epileptogenesis, and levels of these inflammatory factors may serve as biomarkers for epilepsy." (PMID 39249163, 2024). "There is an array of evidence that IL-1β/IL-1R1 is correlated with epilepsy severity." (PMID 38087170, 2024). "Similarly, in a study of children with epilepsy aged 4 to 17 years, the investigators also found higher IL-1β in the severe epilepsy group than in the control group." (PMID 38564049, 2024). "Furthermore, some inflammatory mediators, such as TNF‐α, IL‐1β, and IL‐6, play a significant role in the development of epilepsy, and Crocin presents an inhibitory effect on these inflammatory cytokines." (PMID 38775292, 2024). "IL-1β is commonly elevated in the serum and cerebrospinal fluid (CSF) of patients with epilepsy." (PMID 38074156, 2023). "Moreover, the interleukin converting enzyme (ICE)/caspase-1, able to inhibit the conversion of pro-IL-1b to the pro-convulsant IL- 1b, has been recently contemplated as a possible target for the management of drug-resistant epilepsies." (PMID 38078329, 2023). "Increases or overexpression in IL-1β have been found in human patients with TLE, HS and cortical dysplasia tissue, TBI associated epilepsy, and tumor associated epilepsy." (PMID 39086689, 2023). "Immunoreactive beta-amyloid and IL-1β levels were elevated in the human temporal lobe tissue of surgically resected patients with refractory epilepsy, and the number of microglia was three times higher in patients with epilepsy than in controls." (PMID 36518035, 2023).
epilepsy (continued). "Furthermore, the usefulness of anakinra has already been reported in epilepsy, in which IL-1β is deeply involved in the pathogenesis, and which has been pointed out to have pathophysiological similarities with migraine." (PMID 37176049, 2023). "In a study involving epilepsy by inducing upregulation of IL-1β and TNF-α mRNA was shown to be blocked by anti-HMGB1 through a potential anti-inflammatory mechanism that could inhibit microglia activation and proinflammatory cytokine synthesis." (PMID 36310854, 2022). "Immunological methods using flow cytometry could facilitate the measurement of IL-1β levels, which remains challenging to assess, thereby contributing to immunological studies of epilepsy." (PMID 35054141, 2022). "All of these results suggest that the deregulation of IL-1β levels may differ in various types of epilepsy, suggesting the contribution of different molecular pathways to their etiology." (PMID 35326336, 2022). "In particular, data suggested that Il1β might play a role in the pathophysiology of epilepsy through increasing glutamatergic signalling and N-methyl-d-aspartate (NMDA) receptor activity, and decreasing GABAergic transmission." (PMID 35897817, 2022). "Proinflammatory cytokines (IL-1β, IL-6, and IL-18) contribute to the pathophysiology of epilepsy through several pathways: modulating glutamatergic transmission, enhancing N-methyl-D-aspartate receptor function by activation of SRC tyrosine kinase, and altering GABAergic neurotransmission." (PMID 35624482, 2022). "In comparison with the epilepsy group, the seizure frequency, duration, and seizure power, the mRNA and protein expressions of IL-1β and IL-1R1, the expressions of RhoA and ROCK I proteins, and the ratio of RhoA protein between membrane and cytosol decreased in the electrical stimulation group." (PMID 35119588, 2022). "Since IL-1β voided the effect of IL-10 on GABA currents, this supports that the resolution mechanisms of the pathogenic neuroinflammatory response may fail in epilepsy, thus allowing the ictogenic effects of the concurrent inflammatory molecules to prevail." (PMID 36289354, 2022). "It has been suggested that IL-1β/ IL-1R1 expression correlates with epilepsy severity." (PMID 35837232, 2022). "The mechanism of epilepsy induced by IL-1β-mediated neuroimmune inflammatory responses is complex." (PMID 35837232, 2022). "To date, modulation of neuroinflammation by the GM through uncontrolled activation of Th-17, production of IL-1-b, IL-6, and TNF-α, as well as a reduction of SCFAs that result in BBB alterations, are the only known causal interactions that determine the onset of epilepsy." (PMID 36138769, 2022). "Moreover, results of clinical investigation disclosed a relationship between cerebrospinal fluid IL1-β levels and an allelic variant of the IL1-β gene to the risk of developing epilepsy." (PMID 36278003, 2022). "One of the widely studied cytokines in epileptic patients and animal epilepsy models is IL-1β." (PMID 35326336, 2022). "In human brain tissue resected during epilepsy surgery, elevated expression of IL-1β and IL-1RA was found in focal cortical dysplasia (FCD) and glioneuronal tumors, as well as in cortical tubers and giant cell astrocytoma in patients with tuberous sclerosis and in hippocampal sclerosis." (PMID 35625063, 2022). "Previous studies demonstrated that different inflammatory mediators, including tumor necrosis factor (TNF)-α, IL-1β, and IL-6, may contribute to epilepsy development and progression." (PMID 35647304, 2022). "The plasma concentrations of IL-1β and IL-6 may have potential utility as peripheral biomarkers of immune system activation in the course of epilepsy and translational potential for future clinical use." (PMID 33377994, 2021).
epilepsy (continued). "Interestingly, invasive electrical stimulation of other brain regions also attenuates neuroinflammation: high-frequency deep brain stimulation (DBS) (130 Hz) of the anterior thalamic nucleus resulted in a decrease of TNF-α and IL-1β in a rat model of epilepsy." (PMID 33514001, 2021). "This set of evidence highlights that serum IL-1β may represent a biomarker for epilepsy as an ongoing neuroinflammation." (PMID 34976232, 2021). "We hypothesize that by reducing NLRP3 activation in the neonatal brain, the inhibition of IL-1β expression would substantially ameliorate epilepsy after HIBD, as well as improve learning and memory abilities." (PMID 34046147, 2021). "Notably, IL-1β was also one of the most highly upregulated genes in the brains of patients with epilepsy." (PMID 34511110, 2021). "Receiver operating characteristic (ROC) curve analysis showed that the area under curves was 0.808 when the best cut-off value of IL-1β was 5.42, which could be used as a biomarker of recurrent epilepsy after stroke." (PMID 33959658, 2021). "LTC inhibits IL‐1b inflammatory responses and reduced reactive gliosis in the hippocampus and piriform cortex in a rat model of epilepsy suggesting it could be an important agent in the prevention of epileptogenesis." (PMID 33666367, 2021). "Notably, in epileptiform conditions, IL-1β, a neurotoxic cytokine and one of the cytokines chiefly involved in the pathogenesis of epilepsy, prominently contributes to the morphological changes in the pericytes." (PMID 34209145, 2021). "Finally, similar to KC/GRO levels, no changes were observed between conditions (control vs. status epilepticus/epilepsy) in plasma concentrations for IL-1β, IL-6, or IL-18 in wt mice." (PMID 34572093, 2021). "Moreover, the expression of several cytokines downstream of P2X7R activation (e.g., IL-1β, IL-18) has been found altered in the blood of patients with epilepsy." (PMID 34572093, 2021). "In our study, CARD8 rs2043211 T allele was associated with a lower frequency of epilepsy after HIE after the adjustment for neonatal convulsion, but its association was nominally significant only in interaction with IL1B rs16944 after adjustment for neonatal convulsions." (PMID 34573127, 2021). "No changes could be observed in plasma levels between genotypes for IL-1β and IL-6 post-status epilepticus and during epilepsy." (PMID 34572093, 2021). "Also, we do not claim that the CSF1R pathway is the only contributor in neuro-inflammation as others have already been extensively validated in epilepsy, including IL-1β signaling." (PMID 33819288, 2021). "Some reports have indicated that inflammation may extend beyond the CNS, and increased levels of proinflammatory cytokines such as IL-1β and IL-6 have also been observed in the blood of epilepsy patients." (PMID 33377994, 2021). "In epilepsy models, meloxicam diminished IL-1β and TNF-α levels." (PMID 34573138, 2021). "In this study, we could also observe that in the epilepsy group, caspase-1 and IL-1β presented increased levels when compared to the control group." (PMID 32219137, 2020). "Furthermore, the exosomes significantly inhibited the release of TNF‐α and IL‐1β, and cytokine release was further decreased by circHivep2+ exosomes in the hippocampus at 72 hours after KA‐induced epilepsy." (PMID 33002329, 2020). "Furthermore, an important correlation between IL-1β vs. caspase-1 and IL-6 vs. caspase-3 was observed in the epilepsy group (VV genotype)." (PMID 32219137, 2020). "IL-1β, IL-6, caspase-1, and caspase-3 levels were increased in the epilepsy group (VV genotype)." (PMID 32219137, 2020). "An inhibitor of IL-1β synthesis is being studied in patient with treatment-resistant epilepsy." (PMID 32973652, 2020). "However, further studies including larger sample sizes and neurocognitive testing are needed to confirm the usefulness of serum α-synuclein and IL-1β as prognostic biomarkers for epilepsy." (PMID 32151248, 2020).
epilepsy (continued). "Accordingly, our results demonstrated an interesting correlation between IL-1β and caspase-1 in the epilepsy group–generalized seizures (VV genotype), corroborating with previous studies, emphasizing the great importance of Ala16Val MnSOD SNP seizure type in the obtained results." (PMID 32219137, 2020). "Pearson's analysis demonstrated in the epilepsy group which presented generalized seizures (VV genotype), an interesting correlation between inflammatory and apoptotic parameters: IL-1β vs. caspase-1 (r = 0.7, p < 0.05) and IL-6 vs. caspase-3 (r = 0.6, p < 0.05)." (PMID 32219137, 2020). "The direct correlation between IL-1β and excitotoxicity has been described and its involvement in neurodegeneration has been observed in different neurological disorders such as epilepsy and multiple sclerosis." (PMID 31920563, 2019). "Therefore, concentration of IL-1β in the peripheral blood of dogs with traumatic brain injury and epilepsy was investigated, as well as its presence in cerebrospinal fluid (CSF) of dogs with epilepsy using an Enzyme-Linked Immunosorbent Assay (ELISA)." (PMID 31208341, 2019). "Also, the increased IL-1β in the blood of dogs with epilepsy, confirms the involvement of inflammation in the pathophysiology of the disease." (PMID 31208341, 2019). "Thus, ketosis suppresses inflammatory signaling (e.g., NLRP3/TLR4/IL-1R/NF-κB) signaling pathways and proinflammatory cytokines/enzymes (e.g., IL-1β and COX-2) that are linked pathophysiologically to epilepsy and other seizure disorders." (PMID 31680801, 2019). "The source of IL-1β in the peripheral blood could also represent a mixture between the central and the peripheral response of the immune system to epilepsy, by the activation of microglia as well as peripheral monocytes." (PMID 31208341, 2019). "This remarkable result suggests that regardless of the cause of epilepsy, IL-1β is elevated in blood." (PMID 31208341, 2019). "Pro-inflammatory cytokines and IL-1β are potentially involved in the pathophysiology of epilepsy." (PMID 31208341, 2019). "The leakage of the BBB that occurs, could lead to the increase of the IL-1β in blood, which explains the cytokine detected in our dogs with epilepsy." (PMID 31208341, 2019). "In this study, we have detected increased IL-1β in serum of dogs with epilepsy regardless of the cause." (PMID 31208341, 2019). "We hypothesized that there is an elevation of IL-1β in serum and CSF of dogs with epilepsy, as well as in serum of dogs with TBI, reflecting involvement of this cytokine in pathophysiology of naturally occurring canine epilepsy in a clinical setting." (PMID 31208341, 2019). "IL-1β is involved in the pathogenesis of epilepsy in a variety of ways." (PMID 30514296, 2018). "Cytokine IL-1β has also been found to be significantly increased within the cerebrospinal fluid (CSF) in the epileptic pediatric population as opposed to the control group, suggesting the cytokine’s important role in epilepsy initiation and progression." (PMID 29764485, 2018). "The generated hypothesis involves interleukin-1 beta (IL-1 beta) and glutamate, and suggests that IL-1 beta influence on glutamate levels is involved in the etiology of both epilepsy and inflammatory bowel disease." (PMID 30587224, 2018). "Prior studies demonstrate that elevated levels of interleukin-1β (IL-1β), interleukin-6 (IL-6), interleukin-8 (IL-8), and tumor necrosis factor (TNF) are linked to neuronal hyperexcitability and are found in serum and CSF of patients with epilepsy." (PMID 30344507, 2018). "Astrocytes contribute to chronic neuroinflammation in epilepsy not only as the major source of IL-1β, but also due to their role in K+ buffering, uptake of extracellular glutamate, glutamine supply for presynaptic terminals as well as the ability to control synaptogenesis." (PMID 30031401, 2018).